TFRC (transferrin receptor)
Diseases named in the same sentence as TFRC in open-access papers (continued):
Sharing a sentence is not in itself a finding about the gene and the disease.
iron deficiency (continued). "The following cut‐off points were applied: iron deficiency [ferritin < 12 μg/L or soluble transferrin receptor (sTfR) > 8.3 mg/L], vitamin A deficiency (retinol‐binding protein < 0.69 μmol/L) and zinc deficiency (serum zinc < 65 μg/dl for morning sample and <57 μg/dl for afternoon sample)." (PMID 34897980, 2022). "The ferrireductase DCYTB was apically expressed on choroid plexus epithelial cells, suggesting that they import iron from the CSF via DMT1 and its coupled DCYTB; conversely, the expression of the transferrin receptor (TfR1) had a basolateral pattern and was increased in iron deficiency." (PMID 33220123, 2021). "Serum transferrin receptor (TfR) concentration and the ratio of serum TfR to serum ferritin may be another indicator of iron deficiency to consider in future." (PMID 34447779, 2021). "An analysis of the 35 patients consisted in evaluating iron homeostasis including hepcidin, markers of erythroid iron deficiency (soluble transferrin receptor (sTfR) and erythrocyte protoporphyrin (PPIX)), expression of duodenal iron transporters (DMT1 and ferroportin) and inflammatory markers." (PMID 34444676, 2021). "Soluble transferrin receptor (sTfR) is a promising indicator of iron deficiency anemia (IDA)." (PMID 32320096, 2020). "The authors reported the total analytical error of a photonic crystal (PC) biosensor in the determination of ferritin and soluble transferrin receptor (sTfR) as biomarkers of iron deficiency anemia in chronic kidney disease (CKD) patients against certified ELISAs." (PMID 32092986, 2020). "However, iron deficiency prevalence, defined by low serum ferritin, was 5.9% and by serum transferrin receptor was 3.1%." (PMID 31940318, 2020). "We hypothesized that the haematopoietic progenitors the most sensitive to iron deficiency should have higher metabolic demand for iron, reflected by higher expression of transferrin receptor (Tfrc) protein on the cell surface." (PMID 31015568, 2019). "Of note, iron and zinc were not identified as problem nutrients in the present study, despite prevalences of iron deficiency (low ferritin and high soluble transferrin receptor) and low plasma zinc concentrations ranging from 21–41% among pregnant women in the same study area." (PMID 30609695, 2019). "Among the biomarkers recommended by the World Health Organization (WHO) for assessment of iron status, a combination of ferritin and soluble transferrin receptor (sTfR) levels reflects the full spectrum of iron status from normal iron stores to tissue iron deficiency." (PMID 30885726, 2019). "Elevated soluble transferrin receptor levels in plasma are associated with iron deficiency." (PMID 29666917, 2019). "An increase in transferrin receptor protein more specifically indicates iron-deficiency anaemia." (PMID 31042781, 2019). "Therefore, the failure to further increase transferrin receptor expression suggests that the developing brain is particularly vulnerable to severe iron deficiency." (PMID 31416268, 2019). "In the absence of bone marrow biopsies, ferritin remains the gold standard to assess iron deficiency, and although other markers of iron deficiency have been explored, such as the soluble transferrin receptor, they currently lack established definitions for iron deficiency in pregnancy." (PMID 30231938, 2018). "Furthermore, iron deficiency, this time defined by increased circulating soluble transferrin receptor levels, was associated with disease severity and poor clinical outcome." (PMID 29904352, 2018). "Increased transferrin receptor mRNA also indicates iron deficiency." (PMID 29324800, 2018). "And iron deficiency anemia is observed in a mouse model of missense mutation in TFRC." (PMID 28915649, 2017).
iron deficiency (continued). "In bivariate analysis, both whole blood and erythrocyte ZPP were strongly elevated in iron deficiency, anaemia and Plasmodium infection; they declined with increasing haemoglobin and plasma ferritin concentrations; and they increased with plasma transferrin receptor concentration." (PMID 28770094, 2017). "Although serum transferrin receptor may overestimate iron deficiency in populations in whom inflammation is common, for example in malaria endemic regions we do not consider that inflammation was prevalent in our study." (PMID 29155855, 2017). "Anaemia as measured in the whole population sample (defined by low Hb according to gender; 8.1%) was markedly more common than the estimate of iron deficiency anaemia (defined by low Hb, low ferritin and raised serum transferrin receptor; 3.9%) based on the weighted population." (PMID 29155855, 2017). "First, it has been suggested that over-expression of TFRC may be a response to intracellular iron deficiency during liver carcinogenesis." (PMID 26657500, 2016). "On the other hand, regarding the importance of iron deficiency on growth and development, further investigations indicating transferrin receptor, zinc protoporphyrin, CRP along with frerritin may be more useful to address exact prevalence of IDA." (PMID 26985355, 2015). "Additionally, soluble transferrin receptor (sTfR) is a good indicator of absolute iron deficiency and/or iron restricted erythropoiesis in patients with inflammation." (PMID 26517509, 2015). "Based on our criteria for iron deficiency (ferritin < 20 μg/L, haemoglobin 115–165 g/L, soluble transferrin receptor 0.9–2.30 mg/L, A1GP 0.51–1.17 g/L), at follow-up six (75%) iron deficient participants on 60 mg iron became iron sufficient and one remained iron deficient (13%)." (PMID 24714351, 2014). "Diagnosis of iron deficiency based on ferritin (the current standard test) may be enhanced by the addition of serum soluble transferrin receptor (sTfR) assay." (PMID 24244281, 2013). "Lastly, to further confirm that the livers were “sensing” iron deficiency in animals receiving an iron-deficient diet, the mRNA abundance of the iron uptake protein transferrin receptor 1 (Tfr1) and the iron-sensing peptide hormone hepcidin (Hamp1) was assessed." (PMID 23110872, 2012). "The authors postulated that RLS may result from decreased iron regulatory protein 1 in neuromelanin cells resulting in destabilization of the transferrin receptor mRNA and therefore cellular iron deficiency." (PMID 23211049, 2012). "The findings from this study highlight the dilemma of distinguishing iron deficiency anemia from AI, which remains a frequent clinical challenge despite the availability of tests such as the soluble transferrin receptor (sTfR), a marker of increased erythropoiesis and iron deficiency." (PMID 20368776, 2010). "The correlation between high-fluorescence reticulocytes and soluble transferrin receptor in iron-deficiency anemia may be explained by a high concentration of transferrin receptor synthesized as response to decreased iron content in red blood cell progenitors." (PMID 12870058, 2003). "Soluble transferrin receptor (sTfR) and Reticulocyte Hemoglobin (Ret-He) assessment can be helpful, especially in inflammation-related cases where ferritin levels may be misleading, potentially masking severe iron deficiency." (PMID 40648893, 2025). "Neurohormonal activation may induce changes in the regulatory molecules of cellular iron homeostasis, resulting in downregulation of mRNA expression of transferrin receptor 1 and inactivation of iron regulatory proteins, thus leading to intracellular iron deficiency and mitochondrial dysfunction." (PMID 39196095, 2023). "However, cellular transferrin receptor expression is also influenced by inflammation, which may negatively affect the sensitivity of sTfR levels to indicate true iron deficiency in the presence of inflammation." (PMID 33670067, 2021).
iron deficiency (continued). "Therefore, the inclusion of soluble transferrin receptor (sTfR) could be of additive value for iron-restricted erythropoiesis, as elevated levels of sTfR reflect both erythroid activity and functional iron deficiency." (PMID 32816244, 2020). "Erythro-myeloid progenitors expressed less transferrin-receptor on the cell surface and had less labile iron compared to primitive erythroid progenitors, which could reduce their capacity to compete for scarce iron and survive iron deficiency." (PMID 31015568, 2019). "Therefore, we suggest that hepcidin as well as transferrin receptor might be useful in the assessment of iron metabolism in children (especially vegetarians), in order to prevent subclinical iron deficiency." (PMID 28342014, 2017). "Serum ferritin, transferrin receptor and iron were measured in 1196 students with low red cell indices and in 513 with normal red cell indices and these results were weighted to estimate the frequencies of iron deficiency and iron deficiency anaemia for the whole student population sample." (PMID 29155855, 2017). "Also, it can be due to the upregulation of transferrin receptor synthesis in the case of iron deficiency, which enables placenta to compete more effectively for circulating transferrin iron with erythroid marrow of the pregnant mothers intending adequate iron supply of the growing fetus." (PMID 25734012, 2015). "IDA, iron-deficiency anemia; TSAT, transferrin saturation; CHr, reticulocyte Hgb content; HRC%, percentage of hypochromic red blood cells; sTfR, soluble transferrin receptor; NGAL, neutrophil gelatinase-associated lipocalin." (PMID 39958087, 2025). "Iron deficiency (as defined by MCV, ferritin, CRP and soluble transferrin receptor serum levels) and low hemoglobin levels simultaneously were detected in 48 patients (n = 48/155; 31%)." (PMID 40759730, 2025). "A working group from the World Health Organization has recommended five biomarkers for the work-up of iron deficiency, namely haemoglobin, mean cell volume (MCV), zinc protoporphyrin, soluble transferrin receptor, and serum ferritin." (PMID 39507475, 2024). "Consistent with decreased kidney iron content, kidney macrophages in CKD showed intracellular iron deficiency as indicated by lower LIP and higher transferrin receptor 1 (TfR1 or CD71) compared with control kidney macrophages." (PMID 36394951, 2023). "The diagnosis of iron deficiency is based on the values of ferritin level, iron transferrin saturation (TfS), total iron-binding capacity (TIBC), and soluble transferrin receptor (sTfR) concentration." (PMID 36140459, 2022). "The RCTs confirmed that H. pylori are associated with iron deficiency anemia by demonstrating improvement in markers of iron status (ferritin, hemoglobin, Mean Corpuscular Volume (MCV), serum transferrin receptor levels) with H. pylori eradication therapy." (PMID 36133500, 2022). "Our objectives were to determine the impact of supplementing diets with 1 egg/d on 1) plasma ferritin, soluble transferrin receptor (sTfR), body iron index (BII), and hemoglobin concentrations and 2) the prevalence of iron deficiency (ID), anemia, and IDA." (PMID 35755939, 2022). "Inflammation and systemic iron deficiency cumulatively enhance gene expression of ileal mucosal HIF1A and TFRC, where circulating free iron negatively associates with TFRC expression." (PMID 35755436, 2022). "Activated NK cells increase expression of transferrin receptor (CD71), whereas iron deficiency results in a lose function of NK cells." (PMID 35401569, 2022). "Several parameters lead to diagnose systemic (serum ferritin, serum iron, serum transferrin, and transferrin saturation levels) and/or erythroid (serum transferrin receptor (sTfR) and erythrocyte protoporphyrin (PPIX)) iron deficiencies." (PMID 34444676, 2021).
iron deficiency (continued). "During cellular iron deficiency, IREB2 and ACO1 induce iron acquisition and retention by stabilising mRNAs that encode iron uptake proteins such as TFRC while blocking translation of mRNAs that encode proteins involved in iron sequestration and egress." (PMID 34880854, 2021). "The mRNA of the transferrin receptor (Tfrc) and the divalent metal transporter-1 (DMT1), known as Slc11a2, contain an IRE in their 3′ untranslated region and are upregulated in iron deficiency." (PMID 33553263, 2020). "Compared with other key roles in iron homeostasis (such as in activating CYBRD1), we found that TFRC, and IRP2 upregulation, and FTH1 downregulation were significantly induced after incubation with the miR-17-5p inhibitor in a degree of iron deficiency." (PMID 31423010, 2019). "We demonstrate that these cells with loss of miR-485-3p function are in a greater state of iron deficiency, as evidenced by increased levels of IRP2 protein, increased TFRC mRNA expression, and decreased ferritin light chain (FTL) mRNA expression." (PMID 23593016, 2013). "Elevated levels of the soluble transferrin receptor (sTfR), a biomarker, were used to assess increased demand for iron due to red blood cell production, which can indicate iron deficiency anemia rather than other anemia types." (PMID 40600692, 2025). "We have also not measured other biomarkers of iron deficiency like serum soluble transferrin receptor." (PMID 36599872, 2023). "In iron-deficiency patients, serum levels of ferritin, transferrin saturation, and hepcidin were lower, while those of soluble transferrin receptor and transferrin were higher than in the non-iron deficiency patients." (PMID 36986182, 2023). "Moreover, the hydrolyzed red lentil protein + iron complexes in vitro decreased the expression levels (DMT—Divalent metal transporter 1, TFR—Transferrin receptor, and ANKRD—Ankyrin repeat domain 37 mRNA) which were induced due to iron deficiency anemia." (PMID 37959017, 2023). "Specifically, under conditions of iron deficiency, IRE/IRPs interactions promote the uptake of iron by stabilizing transferrin receptor (TFRC) and DMT1 mRNAs against the degradation and preventing its sequestration and efflux, inhibiting the translation of ferritin, ferroportin, and ALAS2." (PMID 36769209, 2023). "Other parameters like percentage of hypochromic red blood cells, reticulocyte hemoglobin content and soluble transferrin receptor have been suggested as markers of true iron deficiency in CKD but are either not widely available or have not been found useful." (PMID 36599872, 2023). "Few other studies reported an increase in the prevalence of iron deficiency in obese adults with significantly lower serum iron level and higher soluble transferrin receptor level than non-obese adults." (PMID 37262022, 2023). "In hypoxia or iron deficiency, the expression of hypoxia-inducible factors (HIF-1α and HIF-2α) increases, and these proteins bind to the HRE in the promoter of TFRC, thereby promoting TFRC transcription." (PMID 36013382, 2022). "A limitation of this study is that measures of iron-deficiency anemia were not performed including plasma ferritin, hepcidin, soluble transferrin receptor, and transferrin." (PMID 36014824, 2022). "Serum levels of ferritin, transferrin saturation, and muscle iron content were lower in the iron deficiency than in non-iron deficiency patients, while those of the soluble transferrin receptor and transferrin were higher in the former patients." (PMID 36235581, 2022). "A significant decrease in theanemic condition in caco-2 cellswas observed by looking at the mRNA levels of marker genes (divalentmetal transporter-1 (DMT1), transferrin receptor (TFR), and ankyrinrepeat domain 37 (ANKRD37)) that were induced by iron deficiency anemia." (PMID 35755397, 2022).
iron deficiency (continued). "Iron deficiency (ID), where the body has insufficient iron for normal function, is clinically characterized by a decrease in serum iron and transferrin saturation (TSAT) and an increase in soluble transferrin receptor (sTfR)." (PMID 35562883, 2022). "The association of hemoglobin, serum ferritin, and soluble transferrin receptor (sTfR) levels to the probability of becoming positive and negative deviants should be discussed in context of iron deficiency and nutrition-infection interaction." (PMID 35405659, 2022). "We also did not assess a comprehensive set of biomarkers to understand iron deficiency (e.g., hepcidin, transferrin receptor protein), nor did we assess hemoglobinopathies." (PMID 33918630, 2021). "Neither does the model account for the increased TFRC expression that would occur in response to iron deficiency at low TSAT values." (PMID 34880854, 2021). "According to our findings from biochemical measures of haemoglobin, ferritin, and soluble transferrin receptor (sTfR), we found little evidence of iron deficiency anemia among women regardless of the biomarker used." (PMID 32530922, 2020). "However, soluble transferrin receptor (sTfR), ferritin, iron or hemoglobin levels were similar, as well as the mean corpuscular volume (MCV), a sign of an iron deficiency-independent alteration of the FPN-hepcidin axis." (PMID 32752277, 2020). "In the TMD group, we observed some patients with elevated levels of transferrin receptor (TfR) and low erythrocyte volume fraction (EVF), which potentially could indicate iron deficiency or an increase in erythropoiesis." (PMID 31687055, 2019). "Cells with lost miR-17-5p function showed a greater degree of iron deficiency, as evidenced by increased protein levels of IRP2, increased transferrin receptor (TFRC) mRNA expression, and decreased ferritin light chain (FTL) and ferritin heavy chain 1 (FTH1) mRNA expression." (PMID 31423010, 2019). "Soluble transferrin receptor is increased in iron deficiency but unlike ferritin is not confounded by inflammation." (PMID 29762515, 2018). "A recent study in children showed that zinc supplementation did not affect indicators of iron deficiency including plasma ferritin and transferrin receptor." (PMID 29713463, 2018). "Confirmatory tests such as ferritin or soluble transferrin receptor measurement for the diagnosis of iron deficiency are not routinely performed at the selected centres." (PMID 29375620, 2017). "High ferritin with low soluble transferrin receptor (sTfR) levels suggest that iron redistribution and low erythropoietic activity, rather than iron deficiency, contribute to anemia." (PMID 24927015, 2014). "Better parameters to identify iron deficiency such as soluble transferrin receptor (sTfR) are not applied widely." (PMID 25646159, 2014). "The findings were consistent with iron deficiency except that transferrin receptor expression was decreased rather than increased." (PMID 23211049, 2012). "The authors concluded that soluble transferrin receptor was not useful in diagnosing the association of iron-deficiency anemia with heterozygous beta-thalassemia." (PMID 12870058, 2003). "We conclude that soluble transferrin receptor and high-fluorescence reticulocytes are not useful for distinguishing heterozygous beta-thalassemia from iron-deficiency anemia patients, although they provide interesting data concerning erythropoietic activity." (PMID 12870058, 2003). "However, distinguishing between ferritin's role as an acute-phase reactant and true iron deficiency requires additional biomarkers, such as transferrin saturation or soluble transferrin receptor levels, which were not evaluated in this study." (PMID 40698207, 2025).